BCL6 (BCL6 transcription repressor)
Diseases named in the same sentence as BCL6 in open-access papers (continued):
Sharing a sentence is not in itself a finding about the gene and the disease.
B-cell lymphoma (continued). "The human proto-oncogene BCL-6 encodes a BTB/POZ-zinc finger transcriptional repressor that was originally characterized as a regulator of B-lymphocyte development and growth and has been implicated in the pathogenesis of B cell lymphoma and in cancers of many organs, including breast cancer." (PMID 20932331, 2010). "Histopathology revealed B-cell non-Hodgkin lymphoma, confirmed by immunohistochemistry (CD20+, BCL2+, BCL6+, MUM1+, and c-MYC+)." (PMID 42221471, 2026). "We observed a strong decrease in BCL6 at the RNA and protein level in BL and showed a strong correlation between MEF2B and BCL6 transcript levels in a panel of B-cell lymphoma cell lines, primary BL samples, and normal B-cell subsets." (PMID 41992423, 2026). "We recognize several chromosomal rearrangements in the genome of the large B-cell lymphomas, among the most frequent are genes MYC and BCL2 and/or BCL6." (PMID 40126346, 2025). "In our patient, FNA indicated abnormal cytology, and subsequent biopsy confirmed a high-grade B-cell lymphoma expressing CD5 and triple expression of Bcl2, Bcl6, and c-Myc." (PMID 40941668, 2025). "A biopsy of this mass was performed within a few days, and pathology and immunohistochemical examination confirmed the presence of a high-grade B-cell lymphoma, expressing CD5+ and showing triple expression of Bcl2, Bcl6, and c-Myc." (PMID 40941668, 2025). "Double-hit lymphoma (DHL), a subtype of high-grade B-cell lymphoma characterized by rearrangements of MYC and BCL2 and/or BCL6 genes, represents an aggressive form of large B-cell lymphoma." (PMID 40961031, 2025). "The pathological subtypes of R/R B-NHL in this cohort were DLBCL, primary mediastinal lymphoma (PML), primary central nervous system lymphoma (PCNSL) and high-grade B-cell lymphoma (HGBL) with MYC and/or BCL2/BCL6 rearrangement." (PMID 40078989, 2025). "Definitive biopsy with immunohistochemistry confirmed a high-grade B-cell lymphoma, positive for CD5 and demonstrating triple expression of Bcl2, Bcl6, and c-Myc." (PMID 40941668, 2025). "Patient #16 was diagnosed with B-cell lymphoma—follicular (FL), consistent with grade 2–3A based on the proliferation index (CD20+, CD10+, BCL6+, PAX5+, CD23–, Ki-67 ~50%)." (PMID 40572665, 2025). "High-grade B-cell lymphoma with MYC and BCL2 and/or BCL6 rearrangements constitutes a distinct clinicopathological entity characterized by aggressive behavior, inherent resistance to conventional immunochemotherapy, and suboptimal clinical outcomes." (PMID 41364305, 2025). "High-grade B-cell lymphomas with MYC and BCL2 and/or BCL6 rearrangements represent aggressive entities." (PMID 41364305, 2025). "Baseline characteristics were well balanced, with slightly more cases of high-grade B-cell lymphoma with MYC and BCL2 or BCL6 rearrangement in the tisa-cel arm (20% vs. 12%)." (PMID 38893108, 2024). "A total of 222 specimens from 208 unique patients were identified with a large/high-grade B-cell lymphoma diagnosis and performance of either MYC, BCL2, or BCL6 FISH." (PMID 38903717, 2024). "To validate the role of FBW7 in human B-cell lymphoma, we investigated the relationship of BCL6 and FBW7 in human B-cell lymphoma cell lines and found that expression of FBW7 inversely correlated with BCL6 expression." (PMID 38485719, 2024). "A retrospective analysis of all diffuse large B-cell lymphomas and high-grade B-cell lymphomas with MYC and BCL2 and/or BCL6 rearrangements diagnosed between 2017 and 2021 at the Institute of Oncology Ljubljana, Slovenia, has been performed." (PMID 38397877, 2024). "High-grade B-cell lymphoma with MYC and BCL6 rearrangements was much less common in our cohort with 3 cases out of 182 specimens rearranged at both loci (1.6%)." (PMID 38903717, 2024). "One study suggests higher rates of BMB/PET discrepancies among elderly patients and those with high-grade B-cell lymphoma with MYC and BCL2 and/or BCL6 rearrangements." (PMID 38535078, 2024).
B-cell lymphoma (continued). "Fluorescence in situ hybridization (FISH) is an essential ancillary study used to identify clinically aggressive subsets of large B-cell lymphomas that have MYC, BCL2, or BCL6 rearrangements." (PMID 38903717, 2024). "FISH demonstrated MYC, BCL2, BCL6, and CCND1 rearrangements and the diagnosis of high-grade B-cell lymphoma with MYC, BCL2, BCL6, and CCND1 was rendered." (PMID 38914869, 2024). "It was felt to be best considered, as the submitters did, a high-grade B-cell lymphoma with MYC and BCL6 rearrangement with CD5 and SOX11 expression." (PMID 37530792, 2024). "In addition to histologic classification, further testing for rearrangements of MYC, BCL-2, and BCL-6 is important, as these genetic alterations are associated with poor prognosis, particularly the “double-hit” MYC/BCL-2, currently classified by the WHO-HAEM5 as high-grade B-cell lymphoma." (PMID 39749087, 2024). "High-grade B-cell lymphomas with MYC and BCL2 and/or BCL6 rearrangements are known for their aggressive clinical course and so are the ones with MYC and BCL2 protein overexpression." (PMID 38397877, 2024). "DLBCL with rearrangements of MYC, BCL2, and/or BCL6, known as “double-hit lymphoma” (DHL), has been defined as a new entity and renamed “high-grade B-cell lymphoma (HGBCL) with rearrangements of MYC and BCL2 and/or BCL6”." (PMID 38918775, 2024). "B-cell lymphomas with concurrent MYC, BCL2, BCL6, and CCND1 rearrangements appear to be a rare occurrence; however, current standard approaches to DLBCL/HGBL classification do not require routine testing for CCND1 rearrangement." (PMID 38914869, 2024). "Recent updates have removed certain categories, including the previously unclassifiable “B-cell lymphoma” that was identified by “high-grade B-cell lymphoma, with MYC and BCL-2 and/or BCL-6 rearrangements”." (PMID 38535155, 2024). "B-cell lymphomas with MYC and BCL6 rearrangements are now reclassified as a subtype of DLBCL, NOS or HGBL, NOS according to their cytomorphological features." (PMID 38914869, 2024). "In the differential diagnosis, BL needs to be differentiated from other high-grade NHLs, including high-grade B-cell lymphoma, with both MYC and BCL-2, and/or BCL-6 translocations, as well as diffuse large B-cell lymphoma (DLBCL) with MYC translocation." (PMID 39720565, 2024). "The rearrangements involving MYC (MYC-R) are a defining genetic alteration of high-grade B-cell lymphomas (HGBL) carrying BCL2 and/or BCL6 rearrangements, as well as Burkitt lymphoma (BL)." (PMID 37368083, 2024). "A number of other LBCLs are infrequently or rarely show EBV infection such as HHV8+ DLBCL, high grade B-cell lymphoma/DLBCL with MYC and BCL2/BCL6 rearrangements and primary mediastinal LBCL." (PMID 36836878, 2023). "Here, we summarize the different classes of molecules currently under development, which mostly target MYC indirectly in aggressive B-cell lymphomas, paying special attention to subtypes with MYC/BCL2 or BCL6 translocations or overexpression." (PMID 37457123, 2023). "DLBCL/high-grade B-cell lymphoma with MYC and BCL2 and/or BCL6 rearrangements carries a particularly poor prognosis." (PMID 36836878, 2023). "This is in contrast to the more heterogeneous group of aggressive B‐cell lymphomas with MYC and BCL6 rearrangements that are recognized as a provisional entity in the ICC, while they fall into the DLBCL, NOS, or the HGBL, NOS, groups in the WHO-HAEM5." (PMID 36918411, 2023). "Taken together, SC-1 represents a triple-hit B-cell lymphoma cell line, in which IGH rearrangements target FL-specific oncogene BCL2, MYC, as well as a novel target at 17q21, together with fusion of BCL6 and MBNL1." (PMID 37371852, 2023). "Among 76 patients with high-grade B-cell lymphoma, 44 cases (57.9%) were high-grade B-cell lymphoma, accompanied by MYC and Bcl-2 and/or Bcl-6 rearrangement (HGBLR) patients, and 32 cases (42.1%) were HGBL, NOS patients." (PMID 36618391, 2022).
B-cell lymphoma (continued). "Bone marrow tissue biopsy was performed, showing CD20 (+), CD79a (+), CD3 (–), CD5 (-), CyclinD1 (-), Bcl-2 (+), Bcl-6 (-), CD10 (-), MUM-1 (+), and Ki67 (+>50%), and a pathological diagnosis of high-grade B-cell non-Hodgkin lymphoma was made." (PMID 36032118, 2022). "In a subset of B-cell lymphomas, which, based on morphology and phenotype, would be regarded as DLBCLs-NOS, genetic rearrangements of C-MYC, BCL6, and BCL2 have been identified by fluorescent in situ hybridization (FISH) analysis." (PMID 35200580, 2022). "According to 2017 WHO classification, it was reclassified as high-grade B-cell lymphoma with rearrangement of MYC and BCL6." (PMID 35334633, 2022). "HGBL is comprised of two types, i.e., HGBL with MYC and Bcl-2 and/or Bcl-6 rearrangements (HGBL-DH or HGBL-TH) and HGBL-NOS, which replaced the category of B-cell lymphoma, unclassifiable, with features intermediate between DLBCL and BL (BCLU)." (PMID 35686130, 2022). "High-grade B-cell lymphoma with translocations involving MYC and BCL2 or BCL6, usually referred to as double hit lymphoma (DHL), is an aggressive hematological malignance with distinct genetic features and poor clinical prognosis." (PMID 35303910, 2022). "High‐grade B‐cell lymphomas with double or triple hits (MYC plus BCL2 and/or BCL6 genes rearrangements) (HGBL‐DH/TH) are usually highly aggressive lymphomas that respond poorly to conventional chemotherapeutic regimes." (PMID 35846201, 2022). "Not recognized by either NCI or DFCI are the actual high-grade B-cell lymphoma (HGBCL), B-cell lymphomas with MYC translocation together with either BCL2 and/or BCL6 translocation (double hit/triple hit)." (PMID 36387143, 2022). "A biopsy of the hepatic lesion confirmed an infiltration by a high-grade B cell lymphoma with MYC, BCL2 and BCL6 rearrangements." (PMID 36290900, 2022). "The WHO-HAEM4R entity of high-grade B-cell lymphoma with dual rearrangements of MYC and BCL2 and/or BCL6 has been conceptually reframed and reassigned." (PMID 35732829, 2022). "We report here a case of high-grade B-cell lymphoma with MYC and BCL6 rearrangements relapsing as a high-grade plasmablastic neoplasm with MYC and BCL6 rearrangements after R-CHOP and R-EPOCH therapy." (PMID 35004320, 2021). "A practical algorithmic approach for the diagnosis of mature aggressive B-cell lymphoma proposes MYC-R detection first, followed by BCL2 and BCL6 gene analyses in MYC rearranged cases." (PMID 33768318, 2021). "Chromosomal rearrangements commonly occur in B-cell lymphomas, mainly involving BCL2 gene at 18q21 chromosomal locus, BCL6 at 3q27 and MYC at 8q24." (PMID 33768318, 2021). "A total of 170 patients with DLBCL and high-grade B-cell lymphoma with MYC, BCL2, and/or BCL6 rearrangements (DHL/THL), diagnosed and treated in our hospital between 2000 and 2021, were included." (PMID 34830747, 2021). "Other, less frequent translocations found in B-cell lymphomas involved IGK/IGL and BCL3, BCL6, BCL10 or REL or other regions with yet undefined partner genes." (PMID 34210001, 2021). "The dearth of documented consensual clinicopathological characterization of Taiwanese patients with DHL/THL, otherwise designated high-grade B-cell lymphoma (HGBL) with MYC and BCL2 and/or BCL6 rearrangements, informs the present study." (PMID 33807449, 2021). "Double-hit and triple-hit B-cell lymphomas are high-grade B-cell lymphomas defined by the genetic rearrangements of c-MYC and BCL-2 and/or BCL-6, accordingly, by targeted fluorescence in situ hybridization (FISH) studies." (PMID 33692924, 2021). "Double hit lymphoma (DHL)/THL refer to B‐cell lymphoma with MYC accompanied with Bcl‐2 and/or Bcl‐6 gene rearrangements." (PMID 34698437, 2021). "In follicular lymphoma (FL) and diffuse large B cell lymphoma (DLBCL), Bcl6 recruits HDAC3 to repress transcription and trigger B cell lymphoma." (PMID 34926293, 2021).
B-cell lymphoma (continued). "Chromosomal rearrangements involving BCL2, BCL6 and MYC are commonly found in the most frequent B cell lymphomas, namely follicular lymphomas (FLs) and diffuse large B-cell lymphomas (DLBCLs)." (PMID 33768318, 2021). "High-grade B-cell lymphoma, with MYC and BCL2 and/or BCL6 rearrangements (double/triple-hit high grade B-cell lymphoma, HGBL-DH/TH) constitutes a provisional entity among B-cell malignancies with an aggressive behavior and dire prognosis." (PMID 33672644, 2021). "In 2016, the revised World Health Organization (WHO) guidelines classified this special type to a new category named high‐grade B‐cell lymphoma with rearrangements of MYC, BCL2 and BCL6." (PMID 34698437, 2021). "According to the WHO classification, a total of five (17.2%) patients were, therefore, reclassified as aggressive B-cell lymphoma with MYC, BCL2, and/or BCL6 rearrangements (DHL/THL)." (PMID 34830747, 2021). "Histone deacetylation has been shown to downregulate Bcl-6 activity, and TSA treatment can accumulate inactive acetylated Bcl-6, thus leading to cell cycle arrest and apoptosis of B-cell lymphoma cells." (PMID 34512154, 2021). "On the other hand, the result of CD20 (+), CD10 (−), BCL‐6 (−), and MUM‐1 (+) showed that cells were non‐GCB in B‐cell lymphoma." (PMID 36618443, 2021). "Currently, the term High-grade B-cell lymphoma with MYC and BCL2 and/or BCL6 rearrangements is used." (PMID 34945004, 2021). "The result of CD20 (+), CD10 (+), BCL‐6 (+), and MUM‐1 (−) indicated that cells were germinal center B cell‐like (GCB) in B‐cell lymphoma." (PMID 36618443, 2021). "The recently revised World Health Organization (WHO) classification of tumors of hematopoietic and lymphoid tissues now acknowledges the new and provisional entity of high-grade B-cell lymphoma, with MYC and BCL2 and/or BCL6 rearrangements (HGBL-DH/TH)." (PMID 33672644, 2021). "In the revised fourth edition of the World Health Organization (WHO) classification of lymphoid neoplasms published in 201615, DH/triple-hit (TH) DLBCL was reclassified as high-grade B-cell lymphoma, with MYC and BCL2 and/or BCL6 rearrangements." (PMID 33168821, 2020). "High-grade B-cell lymphoma with rearrangements of MYC and BCL2 and/or BCL6 is an aggressive mature B-cell neoplasm, whereas B-lymphoblastic lymphoma is immature cell proliferation, with a frequent positivity for terminal deoxynucleotidyl transferase." (PMID 32713346, 2020). "This study aims to elucidate the patterns of BCL6, BCL2 and C-MYC gene aberrations among Malaysian B-cell Non-Hodgkin Lymphoma (NHL) using fluorescence in situ hybridization (FISH)." (PMID 31892985, 2020). "HGBL, with MYC and BCL2 and/or BCL6 and HGBL, NOS replaces the 2008 category of B-cell lymphoma, unclassifiable, with features intermediate between DLBCL and Burkitt lymphoma (BCLU)." (PMID 31484540, 2019). "In the light of the newly shaped entity of high-grade B-Cell lymphoma with MYC, BCL2 and or BCL6 aberrations, which was excluded from the current study, however, this was to be expected." (PMID 29731969, 2018). "High grade B cell lymphoma with DH/TH (i.e. concurrent translocations of MYC and BCL2, and/or BCL6) has an adverse prognosis (Grade 2B)." (PMID 30190794, 2018). "In summary, we present a novel “double hit” high-grade B-cell lymphoma cell line, designated DH-My6, with concurrent MYC/IGH and BCL6/IGH rearrangements." (PMID 30323893, 2018). "Activation of CD40 receptors in B cell lymphoma leads to NF-κB- mediated IRF4 transcription factor induction, which represses Bcl-6 expression by binding to the Bcl-6 promoter." (PMID 28476134, 2017).
B-cell lymphoma (continued). "Patients with B cell lymphomas bearing MYC translocation combined with translocation involving other genes, such as BCL2, BCL3, or BCL6, defined as double-hit lymphoma (DHL), have a poor prognosis." (PMID 28595585, 2017). "For example, previous investigation indicated that in contrast to human DLBCL, BCL6 and MUM1/IRF4 rarely expressed in canine B-cell lymphoma." (PMID 28069005, 2017). "According to the 2016 WHO classification revision, patients with DH translocations should be excluded from the DLBCL NOS category and placed within the novel category “High-grade B-cell lymphomas, with MYC and BCL2 or BCL6 translocations”." (PMID 29088292, 2017). "In another study, Oki et al21 analyzed the outcome of 129 cases of DHL at MD Anderson; DHL was defined as B-cell lymphoma with translocations and/or extra signals involving MYC plus BCL2 and/or BCL6." (PMID 27115017, 2016). "The designation double-hit lymphoma (DHL) has been used for a B-cell lymphoma carrying a MYC/8q24 rearrangement in combination with a rearrangement involving either BCL2, BCL6, or rarely other known oncogenes." (PMID 26573234, 2016). "Double hit lymphoma represents up to 14% of the patients with aggressive B-cell lymphoma and MYC/BCL2 DHL is most common, representing approximately 65% of all cases, followed by MYC/BCL2/BCL6 triple hit lymphoma, ~20%, and MYC/BCL6 DHL, ~15%." (PMID 27203548, 2016). "We tested two BCR signaling inhibitors (SYK inhibitor R406 and IKKβ inhibitor BMS345541) in three B cell lymphoma cell lines derived from GCB-DLBCL (SUDHL4, CD10 +/BCL6 +), ABC-DLBCL (SUDHL8, CD10−/BCL6−) and primary effusion lymphoma (BCBL1, CD10−/BCL6−)." (PMID 26639163, 2015). "The term ‘DH lymphoma’ was initially used to describe mature-B-cell lymphomas with a chromosomal breakpoint affecting the MYC locus in combination with another recurrent breakpoint, such as BCL2, BCL6, BCL3 or CCND1." (PMID 26517511, 2015). "We analyzed 46 B-cell lymphoma (B-NHL) specimens with known karyotypes for translocations of IGH-, BCL2-, BCL6- and MYC-genes." (PMID 24733537, 2014). "Diffuse large B-cell lymphoma cells generally express pan B cell markers such as CD20, CD19, CD22, CD45 and CD79a; seventy percent of tumor cells express BCL-6 protein; CD10 is expressed in 30 to 60% of cases." (PMID 25294404, 2014). "In B cell lymphomas, structural alterations of the BCL-6 promoter region leads to unregulated expression of BCL-6 and lymphomagenesis." (PMID 21925568, 2012). "Histopathologic analysis revealed a malignant B-cell lymphoma with a MYC gene rearrangement in the absence of BCL2 or BCL6 rearrangements, consistent with a high-grade lymphoma." (PMID 41362384, 2025). "Notably, the classification of high-grade B-cell lymphoma characterised by dual rearrangements involving MYC and either BCL2 or BCL6 has been redefined as DLBCL with high-grade B-cell lymphoma with MYC/BCL2 (DLBCL/HGBL-MYC/BCL2)." (PMID 40572636, 2025). "FISH analysis of an aggressive B-cell lymphoma revealed an atypical BCL6 rearrangement with a 1G1F signal pattern, no BCL2 rearrangements, and no IGH::BCL2 fusion." (PMID 41010038, 2025). "The term high-grade B-cell lymphoma with dual rearrangements of MYC and BCL2 and/or BCL6 from the previous edition of WHO has been conceptually reframed and reassigned to diffuse large B-cell lymphoma/high-grade B-cell lymphoma with MYC and BCL2 rearrangements (DLBCL/HGBL-MYC/BCL2)." (PMID 39038016, 2024). "As many as 19% of patients had high-grade B-cell lymphoma with MYC and BCL2 or BCL6-Rearrangement." (PMID 38893108, 2024). "High-grade B-cell lymphoma with MYC and BCL2 rearrangements was detected in 9% of all large B-cell lymphoma specimens, including one case with rearrangements at all three loci MYC, BCL2, and BCL6; MYC and BCL6 rearrangements were found in 1.6% of specimens." (PMID 38903717, 2024). "B-cell lymphomas with MYC, BCL2, BCL6, and CCND1 rearrangements are rare entities." (PMID 38914869, 2024).